RB1CC1 (RB1 inducible coiled-coil 1)
Description:
Involved in autophagy. Regulates early events but also late events of autophagosome formation through direct interaction with Atg16L1. Required for the formation of the autophagosome-like double-membrane structure that surrounds the Salmonella-containing vacuole (SCV) during S.typhimurium infection and subsequent xenophagy (By similarity). Involved in repair of DNA damage caused by ionizing radiation, which subsequently improves cell survival by decreasing apoptosis (By similarity). Inhibits PTK2/FAK1 and PTK2B/PYK2 kinase activity, affecting their downstream signaling pathways. Plays a role as a modulator of TGF-beta-signaling by restricting substrate specificity of RNF111 (By similarity). Functions as a DNA-binding transcription factor. Is a potent regulator of the RB1 pathway through induction of RB1 expression. Plays a crucial role in muscular differentiation. Plays an indispensable role in fetal hematopoiesis and in the regulation of neuronal homeostasis (By similarity).
Synonyms: FIP200; KIAA0203; Cc1; DRAGOU14; ATG17; PPP1R131
Tractability: Small molecule: a structure with a bound ligand is known. PROTAC: ubiquitination databases record sites on it; its protein half-life has been measured.
Gene: Protein-coding gene on chromosome 8 (52,622,458 to 52,745,843, reverse strand). Ensembl gene ENSG00000023287.
Subcellular location: Nucleus; Cytoplasm; Cytoplasm, cytosol; Preautophagosomal structure; Lysosome
Subcellular location (Human Protein Atlas): Cytosol; Nuclear membrane
Pathways (Reactome):
Autophagy: Macroautophagy
Gene Ontology:
Molecular function: protein binding; protein kinase binding; molecular adaptor activity
Biological process: autophagosome assembly; negative regulation of cell population proliferation; regulation of protein lipidation; autophagy; glycophagy; macroautophagy; pexophagy; piecemeal microautophagy of the nucleus; reticulophagy; ribophagy; positive regulation of autophagy
Cellular component: Atg1/ULK1 kinase complex; cytoplasm; cytosol; lysosome; nucleus; phagophore assembly site; phosphatidylinositol 3-kinase complex, class III; endoplasmic reticulum membrane; phagophore assembly site membrane; autophagosome membrane; vacuole
Genetic constraint (gnomAD): Loss-of-function variants: 34 observed, 154.25 expected, observed/expected ratio (o/e) 0.22, 90% interval 0.17 to 0.29. The upper end of that interval is the gene's LOEUF score, 0.29, which puts it in group 1 of 6, group 1 being the genes least tolerant of losing a copy. Missense variants: 1,546 observed, 1,696.6 expected, observed/expected ratio (o/e) 0.91, 90% interval 0.87 to 0.95. Synonymous variants: 589 observed, 574.06 expected, observed/expected ratio (o/e) 1.03, 90% interval 0.96 to 1.1.
Homologues: Orthologues: chimpanzee RB1CC1 (99% identical), macaque RB1CC1 (98% identical), dog RB1CC1 (95% identical), rabbit RB1CC1 (91% identical), rat Rb1cc1 (89% identical), mouse Rb1cc1 (89% identical), pig RB1CC1 (86% identical), guinea pig RB1CC1 (83% identical), tropical clawed frog rb1cc1 (67% identical), zebrafish rb1cc1 (61% identical), Drosophila melanogaster Atg17 (20% identical), Caenorhabditis elegans epg-7 (18% identical).
Diseases named in the same sentence as RB1CC1 in open-access papers:
RB1CC1 is named in the same sentence as 86 diseases in open-access papers, as found by Europe PMC text mining. Sharing a sentence is not in itself a finding about the gene and the disease. The quoted sentences say what the papers report.
breast cancer (47 papers, 2008 to 2025). A primary or metastatic malignant neoplasm involving the breast. "RB1CC1 deletions are associated with increased numbers of mitochondria in haematopoietic stem cells and mice and with breast cancer in humans." (PMID 30704525, 2019). "RB1CC1 is a tumour suppressor and transcriptional promoter of key cell cycle regulator retinoblastoma-1 that has been found to be inactivated in breast cancer by the intriguing means of truncational mutation." (PMID 22348345, 2012). "RB1 inducible coiled-coil 1 (RB1CC1) expression has been shown to be associated with long term survival of breast cancer patients and has been found to have a role in the inhibition G1-S progression and proliferation in breast cancer cell lines." (PMID 22709873, 2012). "As an example, conditional deletion of the gene coding for the ULK1/Atg1 interactor RB1CC1/FIP200 in mammalian epithelial cells restrains the growth of mammary carcinoma tumors induced by polyomavirus middle T antigen, associated with the induction of a prominent type I IFN response." (PMID 34459017, 2021). "Disruption of autophagy mediated by FIP200 (FAK family interaction protein 200 kDa, also known as RB1CC1) reduced mammary tumor cell proliferation and inhibited mammary tumor development in MMTV-Neu mice." (PMID 39247603, 2024). "For instance, miR-20b can negatively regulate autophagy by targeting RB1CC1/FIP200 in breast cancer cells." (PMID 33680910, 2020). "Inhibition of autophagy by deletion FIP200 (also known as RB1CC1) suppresses the development of mammary tumors in a polyoma Middle T-driven breast cancer model." (PMID 27655644, 2016). "Taken together, we have established RB1CC1 as a novel prognostic predictor in a cohort of Japanese breast cancer patients." (PMID 21203526, 2010). "In this report, we have analyzed the correlation between abnormalities in the RB1CC1 pathway and long-term prognosis, because disease-specific death in later periods (>5 years) of the disease is a serious problem in breast cancer." (PMID 21203526, 2010). "A genetic rearrangement of RB1CC1 has also been suggested to be involved in the tumorigenesis of breast cancer." (PMID 20614030, 2010). "In this report, using the hospital-based cohort of 323 breast cancer cases in Japan, we have shown that RB1CC1 status predicts breast cancer-specific survival (DSS)." (PMID 21203526, 2010). "Despite the frequent RB1CC1 deletion in primary human breast cancers, RB1CC1 conditional knockout in mamillary gland and skin failed to promote tumorigenesis." (PMID 19888451, 2009). "Upon the knockout of RB1CC1 (encoding FIP200/ATG17, a one of key component of ULK1 complex), the inactivation of the EGFR-STAT3 signaling axis was observed, and consequently, there was an impairment of ALDH+ breast cancer stem cells’ (BCSCs) tumorigenicity." (PMID 39201332, 2024). "Reduced RB1CC1 forecasts unpleasing prognosis of breast cancer." (PMID 35068326, 2022). "Furthermore, miR-20a has been shown to negatively regulate autophagy by targeting RB1CC1/FIP200 in breast cancer cells and inhibit autophagy induced by leucine deprivation via suppression of ULK1 expression in C2C12 myoblasts." (PMID 27803889, 2016). "Therefore, a positive status of nuclear RB1CC1 expression [RB1CC1(+)] appears to be intimately related to tumor suppression in breast cancer." (PMID 21203526, 2010).
breast cancer (continued). "In addition, the RB1CC1-RB pathway plays an important role in the proliferation of breast cancer cells in vitro, and its genetic rearrangement has been demonstrated in breast cancer tissue in vivo." (PMID 21203526, 2010). "Also present in this list was RB1CC1, a regulator of RB1 expression that has been shown to contain truncating mutations in breast cancers." (PMID 18782450, 2008). "In breast cancer, CREBBP acetylates RB1CC1 at K276, preventing its ubiquitination and degradation, thereby stabilizing RB1CC1, enhancing autophagy, and promoting resistance under stress conditions." (PMID 41213956, 2025). "Distinct cancers rely on unique regulatory circuits: for instance, HCC frequently engages SIRT1–p62 or PCAF–microtubule pathways, whereas breast cancer emphasizes p300/CREBBP-driven stabilization of transcription factors (e.g., HOXB13, RB1CC1)." (PMID 41213956, 2025). "RB1-inducible coiled-coil 1 (RB1CC1) plays a significant role in the enhancement of the retinoblastoma tumor suppressor (RB1) pathway and is involved in breast cancer development." (PMID 21203526, 2010). "By inhibiting RB1CC1, AZI2 accumulates, leading to overactivation of TBK1-IFN, promotion of cytokine expression in breast cancer, CD8T cell infiltration, and improvement of the response of breast cancer to ICI." (PMID 39161768, 2024). "Loss of nuclear RB1CC1 [RB1CC1(−)] correlated significantly with negative PR expression (p = 0.0003) and with a triple-negative [ER(−), PR(−) and HER2(−)] phenotype of breast cancer (p = 0.0003)." (PMID 21203526, 2010). "FIP200 (also known as RB1-inducible Coiled-Coil 1, RB1CC1) was first reported as a regulator of the retinoblastoma (RB) protein, identified as a tumor suppressor in human breast cancer, and recently rediscovered as a mammalian counterpart of Atg17 in the yeast Atg1-Atg13-Atg17 complex." (PMID 23289756, 2013). "RB1CC1 is a novel regulator of RB1 that dephosphorylates RB1 and increases its expression; in addition, a genetic rearrangement of RB1CC1 might be involved in breast cancer tumorigenesis." (PMID 20614030, 2010). "However, RB1CC1's role in clinical progression of breast cancer has not yet been evaluated, so, as a first step, it is necessary to establish its usefulness as a tool to evaluate breast cancer patients." (PMID 21203526, 2010).
breast cancer (continued). "Although all of the genes in this panel have been reported to have roles in breast cancer, there have been no reports of expression changes in NR3C1 and RB1CC1 genes in response to afatinib, neratinib or gefitinib." (PMID 23816254, 2013).
schizophrenia (8 papers, 2019 to 2025). A major psychotic disorder characterized by abnormalities in the perception or expression of reality. "Cases of schizophrenia with abnormalities in the dentate gyrus have also been associated specifically with RB1CC1 variants." (PMID 40149422, 2025). "Out of the top ten high-risk genes, Sp4 and RB1CC1, the only two DNA-binding transcription factors, bind the same GC-box in regulation of genes involved in the pathogenesis of schizophrenia." (PMID 34750502, 2022). "Given that RB1CC1, a high-risk gene for schizophrenia, binds the more upstream GC-boxes, it is possible that these upstream GC-boxes may also be involved in the pathogenesis of schizophrenia." (PMID 34750502, 2022). "In contrast to Sp1/Sp4 transcription factors that recognize the GC-boxes in the proximal promoter region (−140,−41), the GC-boxes more upstream of this region can be bound by other transcription factors such as RB1CC1, another high-risk gene for schizophrenia from the SCHEMA." (PMID 34750502, 2022). "Mutations or copy number variations in the gene encoding for FIP200 (RB1CC1) were identified in patients affected by psychiatric disorders with developmental delay (DD), autism spectrum disorder (ASD), and schizophrenia (SZ)." (PMID 38201307, 2024). "We studied a patient with schizophrenia, suicidality, and obesity, who carried a de novo RB1CC1 complete duplication, as assessed by high‐resolution array‐CGH." (PMID 33340270, 2021). "Interestingly, NPBWR1 is located in the 8q11.23 region, neighboring the RB1CC1 gene, and two NPBWR1 duplications are associated with schizophrenia, making this gene potentially interesting in yet another disease context." (PMID 39433904, 2025). "Also, a large-scale exome sequencing study identified single genes whose rare mutations substantially increase the risk for schizophrenia, of which six genes (SETD1A, CUL1, XPO7, GRIA3, GRIN2A, and RB1CC1) showed odds ratios larger than ten." (PMID 36878965, 2023). "We hypothesized a pathogenetic model that might explain the correlation between RB1CC1 overexpression and schizophrenia by altering different cell signaling pathways, including autophagy, a promising therapeutic target for schizophrenic patients." (PMID 33340270, 2021). "Interestingly, RB1CC1 binds the same GC-box sequence GGGCGG but more upstream of TSS than Sp4, highlighting the importance of the GC-box in the regulation of genes involved in the pathogenesis of schizophrenia." (PMID 34750502, 2022). "It is unproven whether the RB1CC1 pathogenesis in schizophrenia is mediated by haploinsufficiency rather than genuine overexpression of the gene." (PMID 33340270, 2021).
breast tumor (5 papers, 2007 to 2025). "It is worth noting that the deletion of autophagy-related gene RB1CC1 could reduce the mitochondrial mass and oxidative respiration capacity of breast tumor cells, as well as inhibit the phosphorylation of mTOR substrate." (PMID 33796128, 2021).
hepatocellular carcinoma (5 papers, 2020 to 2024). A malignant tumor that arises from hepatocytes. "Mouse models of hepatocellular carcinoma to elucidate the importance of Rb1cc1 in IKE‐based therapy of liver tumourigenesis." (PMID 35220675, 2022). "Through transcriptome sequencing of human hepatocellular carcinoma (HCC) samples, six genes—TSC1, TSC2, PABPC3, HIF1α, RB1CC1 (ATG17), and RPS6KA3 (RSK2)—were found to be associated with HBV infection." (PMID 33059752, 2020). "The roles of RB1CC1 in liver diseases have only been studied in hepatocellular carcinoma (HCC)." (PMID 38481992, 2024). "Increasing studies have linked miRNAs to autophagic regulation during cancer initiation (such as miR-224 targeting SMAD Family Member 4 (SMAD4) in hepatocellular carcinoma (HCC)) and cancer development (e.g., miR-224-3p targeting RB1-inducible coiled-coil protein (RB1CC1) in cervical tumors)." (PMID 34298969, 2021).
prostate carcinoma (5 papers, 2017 to 2025). A carcinoma that arises from epithelial cells of the prostate gland. "In summary, MPD induced the dissociation of RB1CC1 from DRMs and its subsequent nuclear translocation, contributing to ferroptosis of prostate cancer cells." (PMID 41594579, 2025). "Furthermore, miR-133b and its target, RB1-inducible coiled-coil protein 1 (RB1CC1), were reported to be independent prognostic factors for prostate cancer patients." (PMID 28783103, 2017).
leukemia (4 papers, 2014 to 2023). A malignant (clonal) hematologic disorder, involving hematopoietic stem cells and characterized by the presence of primitive or atypical myeloid or lymphoid cells in the bone marrow and the blood. "Furthermore, cryptic genomic alterations involving leukemia-related genes, such as ATP2B2, ANGPT1, ETV6 and RB1CC1, were inferred in the level of array CGH and confirmed by FISH." (PMID 25120648, 2014).
colon cancer (3 papers, 2009 to 2025). "The knockout of autophagy-related genes RB1CC1, ATG9A, and ATG12 significantly increased tumor cell susceptibility to T-cell killing in breast and colon cancers and enhanced the anti-cancer effect of PD-1 and CTLA-4 checkpoint inhibitors." (PMID 40641524, 2025). "In breast and colon cancers, the sensitivity of tumor cells to T-cell killing was significantly enhanced by knocking out autophagy-related genes RB1CC1 (RB1 inducible coiled-coil 1), ATG9A, and ATG12." (PMID 40641524, 2025).
endometrial carcinoma (3 papers, 2019 to 2025). A malignant tumor arising from the epithelium that lines the cavity of the uterine body. "Lebovitz and colleagues Discovered notable alterations in genes associated with autophagy, namely ATG4C, RB1CC1/FIP200, and ULK4, in cases of endometrial cancer." (PMID 38601753, 2024). "Authors found somatic mutations in a number if autophagy genes including RB1CC1/FIP200, WDR45/WIPI4, ULK4, and ATG7 in endometrial carcinoma and clear cell renal carcinoma." (PMID 31850214, 2019). "Remarkably, endometrial carcinomas showed a high number of mutations in ATG4C, RB1CC1/FIP200, and ULK4 genes." (PMID 31850214, 2019).
liver cancer (3 papers, 2021 to 2024). An epithelial or non-epithelial malignant neoplasm that arises from the liver. "RB1CC1 is abnormally expressed in both liver fibrosis and liver cancer, indicating that RB1CC1 is also a marker of liver fibrosis development into liver cancer." (PMID 38481992, 2024). "We next evaluated the importance of RB1CC1 in liver cancer using DEN‐ and CCl4‐induced HCC mouse models, as these are suitable for the study of liver cancer in vivo." (PMID 35220675, 2022). "Therefore, we generated in vivo liver cancer models in WT and Rb1cc1+/– mice." (PMID 35220675, 2022).
Obesity (3 papers, 2019 to 2024). Accumulation of substantial excess body fat. "For example, the RB1CC1 gene has been identified as a marker associated with obesity in chickens, and maturation of embryonic musculoskeletal cells in humans." (PMID 38788487, 2024).
ovarian carcinoma (3 papers, 2012 to 2026). A malignant neoplasm originating from the surface ovarian epithelium.
acute myeloid leukemia (2 papers, 2015 to 2018). Acute myeloid leukemia (AML) is a group of neoplasms arising from precursor cells committed to the myeloid cell-line differentiation. "Another study has also shown that miR-10a inhibited KLF4 and RB1-inducible coiled-coil 1(RB1CC1) regulated cell apoptosis in acute myeloid leukemia (AML)." (PMID 29848383, 2018).